LGR5 (leucine rich repeat containing G protein-coupled receptor 5)
Diseases named in the same sentence as LGR5 in open-access papers (continued):
Sharing a sentence is not in itself a finding about the gene and the disease.
tumor (continued). "In CRC, quiescent Lgr5+ CCSCs contribute minimally to tumor growth under stable conditions." (PMID 41346579, 2025). "We revealed distinct spatial patterns: Lgr5-positive niches were predominantly localized in the central areas of the tumor, Alcam- and Prom1-positive niches were dispersed throughout the tumor regions, while CD44-positive niches were predominantly distributed in the outer regions." (PMID 40069574, 2025). "While in vivo α-LGR5scFv CAR T cells efficacy was apparent, we were unable to evaluate on-target/off-tumour toxicity in LGR5+ stem cell compartments—in vivo toxicology remains a challenge in murine models because α-LGR5 does not cross-react with the murine LGR5 protein." (PMID 40405910, 2025). "Moreover, Gremlin1 neutralising antibodies were able to shrink tumour size and promote Lgr5+ intestinal stem‐cell differentiation, confirming that Gremlin1 can be oncogenic via promoting WNT stem cell signalling." (PMID 40212011, 2025). "Thus, it is important to conduct tumor stage-specific assessments of LGR5 therapies in in vivo models of metastases." (PMID 41194856, 2025). "Unsurprisingly then, when BCL3 was shown in 2019 to enhance β-catenin signaling in a panel of CRC cell lines, that suppression of BCL3 was found to reduce cancer stem cell activity within the tumour populations, as demonstrated by tumoursphere assay and stem cell markers Lgr-5 and Bmi expression." (PMID 38195591, 2024). "In vivo targeting of the pre-B-ALL tumours by treatment with CL-BiTE co-injected with CD8+ T cells led to a significant decrease in tumour burden supporting further development as a novel “off-the-shelf” therapeutic for LGR5+ cancer patients with a functional immune system." (PMID 39169164, 2024). "The presence of LGR5+ CCSCs is associated with a highly aggressive tumor phenotype and poor prognosis, particularly in cases of early-stage CRC, where stem-like cells contribute to tumor development." (PMID 39671082, 2024). "LGR5 is a promising target for cancer therapy because it is overexpressed in various tumor types and stimulates cancer stem cell proliferation and self-renewal, cancer cell mobility, tumor formation, and epithelial-mesenchymal transition." (PMID 39065798, 2024). "LGR5 is crucial for identifying stem-like cancer cells that drive tumor initiation and recurrence." (PMID 39671082, 2024). "We next determined endogenous localisation of LGR5 using immunofluorescence of NALM6 cells and, consistent with overexpressed LGR5 in HEK293T cells and tissue and tumour biopsies, LGR5 localised to intracellular puncta with low observable signal associated with the cell periphery." (PMID 39169164, 2024). "Thus, upon tumorigenesis, PCs dedifferentiate to a state that hampers secretory differentiation leading to specific patterns of tumor histology and gene expression distinct from that of Lgr5-derived tumors." (PMID 38902475, 2024). "Administration of the EREG mAb following irinotecan treatment delayed growth of subcutaneous patient-derived xenografts enriched for LGR5 as well as decreased the number and size of metastatic tumor nodules after IV injection of the patient-derived LGR5+ CRC cells." (PMID 40727266, 2024). "In addition, tumor size was significantly reduced in Lgr5-Cre-ERT2; Cbsfl/fl mice compared with Cbsfl/fl mice." (PMID 38490069, 2024). "Importantly, the expression of CRC markers (CK7 and CK20), Ki67, and expression of CRC stem cell markers (β-catenin and LGR5) demonstrated strong concordance between the PDOs and tumour tissues." (PMID 38413740, 2024). "Indeed, α-LGR5-ADCs have been previously road-tested for targeting LoVo CRC cell tumours as well as an LGR5-expressing ER-PDX tumour model." (PMID 39169164, 2024).
tumor (continued). "These pieces of evidence suggest the greater acquisition of SASP in 28Si compared to the γ-ray or control group in the tumor as well as normal tissue, whereas a lower level of Lgr5-GFP expression was observed after irradiation in normal as well as in tumor tissue." (PMID 39410012, 2024). "Furthermore, pathways enrichment analysis of the scRNA-seq data using IPA suggested that the glycolysis I pathway was significantly inhibited in KO Lgr5 positive tumor epithelial cells." (PMID 38659853, 2024). "Given that STm asparaginase could also antagonise tumour c-Myc expression, effecting organoid growth and Lgr5 expression, we now questioned how protective the STmΔaroA/ΔansB double mutant would be in vivo." (PMID 39558103, 2024). "It has been hypothesised that another subset of tumour cells can phenotypically revert to a stem-like state in response to chemotherapy treatment which replenishes the LGR5+ve CSC population and maintains tumour growth." (PMID 38319453, 2024). "Insights from WNT/Lgr5 studies could be integrated, as cancer stem cells (CSCs) drive tumor initiation, growth, and metastasis, playing crucial roles in drug resistance." (PMID 39769068, 2024). "Tumor differentiation in LN metastasis has been reported to influence prognosis, and its correlation with LGR5 expression may have prognostic significance." (PMID 38787285, 2024). "Furthermore, pathways enrichment analysis of the scRNA-seq data using ingenuity pathway analysis (IPA) suggested that the glycolysis I pathway was significantly inhibited in KO Lgr5 positive tumor epithelial cells." (PMID 39535280, 2024). "Strikingly, oral treatment with STmΔaroA/ΔansB negated this intrinsic tumour control, as evidenced by expression of Lgr5, Smoc2, and Vim, to levels comparable to the PBS control group, in contrast to the STmΔaroA treatment, which reduces expression of these genes." (PMID 39558103, 2024). "Indeed, two previous studies have used ADC versions of two other LGR5 antibodies for killing LoVo cells in vitro and targeting the LoVo cell tumour model in vivo." (PMID 39169164, 2024). "Furthermore, metastasis is primarily driven by LGR5−ve tumour cells that have greater dissemination potential, inducing secondary tumour growth at distant sites through a process of dedifferentiation into LGR5+ve tumour cells." (PMID 38319453, 2024). "However, the specific impact on different cell types, particularly Lgr5+ intestinal stem cells (ISCs), which are crucial for maintaining cellular homeostasis, GI function, and tumor initiation under genomic stress, remains understudied." (PMID 39410012, 2024). "Importantly, treatment withdrawal restores tumour proliferation, however regrowth is specific to cells that acquire LGR5 expression." (PMID 39169164, 2024). "The effect of the LGR5 knockout on tumor formation and growth in vivo remains to be determined." (PMID 39065640, 2024). "To determine whether these s.c. tumor cells expressed Lgr5, we performed Lgr5 mRNA in situ hybridization." (PMID 37746286, 2023). "Human LGR5(+) cells in CRCs were confirmed to serve as CSCs in growing tumor tissues." (PMID 36835075, 2023). "However, current published research showed very limited consideration related to the influence of tumor microenvironment to LGR5 tumor stem cell related tumor treatment." (PMID 37578396, 2023).
tumor (continued). "Interestingly, while widespread evidence has demonstrated that CRC growth is driven by a subset of LGR5+ stem-cell-like tumor cells, their analyses revealed that high-resistant cancer cells (HRCs) represent a distinct cell population." (PMID 36982333, 2023). "In sum, we concluded that specifically depletion of the LGR5 lineage by DT administration inhibited murine organoid and tumor growth and metastasis, which promoted by mutual influence of CAFs and LGR5‐expressing tumor stem cells." (PMID 37578396, 2023). "Furthermore, the expression of EMT genes and oncogenes, including Mmp3, Mmp7, Mmp8, Fn1, Vim, Foxc2, Ctnnb1, Lgr5, Axin2, cMyc, Ccnd1, and Yap1, was significantly high in the tumor of cohoused Nlrp12–/– compared with WT mice." (PMID 37581937, 2023). "In humans, they also found that LGR5 levels are greater in tumor tissues." (PMID 37547759, 2023). "We confirmed that CAFs firmly encircled LGR5+ tumor cells using immunofluorescence staining." (PMID 37578396, 2023). "In this study, we pioneeringly investigated the mutual relationship between tumor fibroblast cell and LGR5‐expressing tumor stem cell, by constructing an innovated co‐culture model constituting of CAF and LGR5+ cells, which allow the culture of both cell types." (PMID 37578396, 2023). "As expected, cytoplasmic and membrane LGR5 stains were observed in the tumor and normal mucosa." (PMID 37686516, 2023). "Thus, upon tumorigenesis, Paneth cells de-differentiate to a state that hampers differentiation toward Paneth cells, leading to specific patterns of tumor histology and gene expression distinct from that of Lgr5-derived tumors." (PMID 36711533, 2023). "We found that co‐implantation of LGR5+ tumor cells and CAFs increased tumor size." (PMID 37578396, 2023). "More recently, LGR5− cancer cells have been distinguished as the majority of migrating and disseminating cells from the primary tumor to the metastatic site, highlighting an important role for LGR5− cancer cells and their intrinsic capability to re-establish the LGR5+ cancer cell population." (PMID 36833408, 2023). "Thus, we further explored the influence of CAFs which directly isolated from tumors to LGR5‐expressing tumor organoid." (PMID 37578396, 2023). "In our previous study, we demonstrated that CAFs could boost the growth of tumor organoids and enhance the percentage of LGR5 expressing cells both in vitro co‐culture system and in vivo mice model." (PMID 37578396, 2023). "Notably, activation of the Wnt pathway is found in such persistent, slow‐cycling LGR5‐expressing tumor cells, and inhibition of both Wnt and Hh is successful in suppressing tumor development." (PMID 37638338, 2023). "Furthermore, we found that specific knockout of LGR5 expressing cells suppressed CAF‐mediated promotion of tumor formation, growth, and metastasis in the experimental mice model." (PMID 37578396, 2023). "In addition, LGR5-targeted ADCs were effective in the eradication of LGR5+ gastrointestinal cancers and the suppression of tumor progression." (PMID 36910604, 2023). "Hence, OSR1 exerts a tumor-suppressing effect by inhibiting the LGR5-mediated activation of JNK signaling." (PMID 37627077, 2023). "Previous finding that defined liver LGR5+ tumor cells as tumor initiating cell population." (PMID 37578396, 2023). "Increased LGR5 protein expression may lead to enhancements in the Wnt/β-catenin signaling pathway and promote tumorigenesis and tumor progression." (PMID 38136437, 2023). "In the lower compartment, single LGR5‐expressing tumor cells are growing for 10 days." (PMID 37578396, 2023). "were able to establish a measure (which was defined as the time CAR-Ts needed to enforce tumoricidal reactions against 50% of the target tumor cells) to opt for a certain LGR5-redirected CAR-T product as their therapeutic candidate for clinical assessment (called CNA3103)." (PMID 38146364, 2023).
tumor (continued). "However, the specific mechanism between LGR5 and the immune-related tumor microenvironment is unclear." (PMID 35967426, 2022). "Therefore, the inflammatory condition likely causes high LGR5 expression in HSCC, thus promoting the proliferation and invasion of tumor cells." (PMID 36288272, 2022). "Furthermore, it was evident an arrangement of tumor cell types reminiscent of the in vivo organization; Lgr5-EGFP cells were positioned at the organoid center, whereas Emp1-TOM+ cells relocated to the boundaries in contact with the fibroblast population." (PMID 36352230, 2022). "Moreover, LGR5 was recently reported to be highly upregulated in gastroenterological carcinoma; the selective ablation of LGR5 + CSCs led to tumor regression, and targeting LGR5 + human colon CSCs enhanced the effects of chemotherapy." (PMID 36372898, 2022). "LyM tumor cells (LGR5+ cells) also highly expressed signature genes of the PT-b cluster." (PMID 35974387, 2022). "Given the data from a colorectal cancer model showing that metastases are more reliant on Lgr5+ CSCs than primary tumours it will be interesting to see if PDAC primary tumours and metastases react differently to CSC ablation, especially given that metastases are the main cause of patient mortality." (PMID 36088504, 2022). "Moreover, we demonstrated the inhibitory effects of LGR5 expression on tumor growth and migration abilities using two HGSC cell lines." (PMID 35778589, 2022). "However, once the Lgr5 + cell consumption was stopped, the tumor regenerated rapidly, indicating that the tumor cannot be eliminated by ablating Lgr5 + cells." (PMID 36348319, 2022). "Yet, it is formally possible that other tumor cell populations, including Lgr5+ cells, may generate metastasis if they reach foreign organs, as suggested by experiments of direct inoculation of tumor cells into the blood stream performed herein and elsewhere." (PMID 36352230, 2022). "LGR5 was localized to the cytoplasm and membrane of tumor cells." (PMID 35154991, 2022). "In papillary thyroid carcinoma, lncRNA BANCR is responsible for maintaining stemness and tumor growth via the c-RAF/MEK/ERK pathway; additionally, it is observed to influence the expression of CSC markers LGR5 and EpCAM, this eventually leads to tumor development." (PMID 36359888, 2022). "Furthermore, our survival analyses and in vitro assays suggested that LGR5 plays tumor suppressive roles in HGSC." (PMID 35778589, 2022). "In primary CRCs, proliferative Lgr5-neg tumor cells gave rise to Lgr5+ cells and HRCs." (PMID 36352230, 2022). "This is especially important when considering clinical treatment as this phenomenon has also been observed in tumours where differentiated tumour cells (non-Lgr5 + ) can be reactivated following cancer stem cell depletion and subsequently dedifferentiate and fuel tumour growth." (PMID 35589755, 2022). "Finally, both Lgr5 − and Lgr5 + cells were observed enriched in liver metastasis, and Lgr5 + cells were required for metastatic tumor growth, indicating that cellular plasticity is a deterministic step in the metastasis process." (PMID 36348319, 2022). "Since CSC markers, LGR5 and NANOG have been shown to be progressively expressed during carcinogenesis and promote cancer cell proliferation and tumor formation, we next evaluated the impact of PCs repression in tumor cells on LGR5 and NANOG expression during tumor progression." (PMID 35267511, 2022). "Moreover, tumor development in the Lgr5-CreER/Apcfl/fl model depends on the activity of the transcription factor Myc and PYCR1 is a Myc target gene, suggesting that the enhanced expression of PYCR1 in CRC plausibly results from Myc transcriptional activity." (PMID 35130302, 2022). "We detected Lgr5-positive tumor cells in 9% (± 19%) of all PC cancer cells." (PMID 35844581, 2022).
tumor (continued). "Furthermore, two independent studies reported that in GC patients treated with neoadjuvant chemotherapy, the rate of positive LGR5 expression was higher in the resected specimens exhibiting poor tumor regression compared to regressed tumors." (PMID 35326607, 2022). "However, ablation of LGR5+ cells only led to short-term tumor regression followed by tumor regrowth with re-occurrence of LGR5+ cells, indicating pronounced cellular plasticity with regard to replenishing the CSC population." (PMID 36358834, 2022). "In addition, LGR5 overexpression results in decreased tumor growth and migratory abilities in HGSC cell lines." (PMID 35778589, 2022). "Moreover, in vitro assays demonstrated that LGR5 expression suppressed tumor proliferation and migratory capabilities." (PMID 35778589, 2022). "Therefore, it is possible that there are specific cellular partnerships between LGR5+ stromal cells and LGR5+ or LGR5− tumor cells." (PMID 35778589, 2022). "Lgr5 − cells replenished the Lgr5 + cell pools to promote tumor growth." (PMID 36348319, 2022). "Although it is known that curcumin can induce autophagy in many tumor cells, whether curcumin can induce autophagy of LGR5(+) colorectal CSCs was unclear." (PMID 33713277, 2021). "Intriguingly, comparable growth dynamics were observed in cultured organoids, suggesting that the repopulation of Lgr5+ cells may partly rely on intrinsic Lgr5− cell properties and proceed independently of tumour-activated stroma." (PMID 33673710, 2021). "In this context, using 5-ASA to prevent the re-expression of LGR5 may not only prevent tumour formation and potentially recurrence after treatment but may also improve the efficacy of conventional therapies, improving the prognosis of patients with CRC." (PMID 33785874, 2021). "Many studies show that LGR5 shows tumor-initiating cells in the intestinal system." (PMID 34452555, 2021). "Thus, it is reasonable to assume that CEA and LGR5 detects partly different CC tumor cell-population, i.e., CEA detects mainly fully differentiated transformed colonocytes, and LGR5 mainly transformed undifferentiated colonocytes." (PMID 35008827, 2021). "This meant that mutated intestinal stem cells (Lgr5+) were radiosensitive, while non-stem cell tumor-initiating clones were radio-resistant." (PMID 33671641, 2021). "Indeed, both the repopulating ability and tumour-initiating potential of Lgr5+ ISCs from NWD1-fed mice were severely impaired." (PMID 33673710, 2021). "Remarkably, while the majority of Lgr5+ subsets are exquisitely sensitive to DNA damage, Krt15+Lgr5+ cells are radioresistant and may thus survive to spawn tumours post injury." (PMID 33673710, 2021). "The mechanisms whereby non-CSCs, or distinct subsets thereof, sense the depletion of Lgr5+ CSCs within a tumour, and the intrinsic and extrinsic cues that trigger their mobilization remain an important avenue for investigation to better understand therapy resistance and tumour recurrence." (PMID 33673710, 2021). "Because LGR5 is a biomarker for hair follicle stem cells, it plays a role in sustaining skin homeostasis, and the cells expressing this protein are thought to be a subset of cells with high stemness that contribute to tumor development." (PMID 34106558, 2021). "In the current study, correlation analysis demonstrated that LGR5 expression in human RC clinical specimens was significantly correlated with depth of tumor invasion, LN metastasis, cTNM stage and MRF involvement, but it was not correlated with gender, age, tumor site, nor pathological features." (PMID 34582650, 2021). "Next, we investigated whether HNK affects CSCs by determining the expression of DCLK1 and LGR5 in tumor tissues." (PMID 34206989, 2021). "Lgr5+ ISCs have been amply demonstrated to serve as tumour-initiating cells." (PMID 33673710, 2021). "However, a few days after treatment, Lgr5+ cells reappeared and tumor growth resumed, indicating a plastic process." (PMID 33671641, 2021).